RNU6-850P (RNA, U6 small nuclear 850, pseudogene)
Synonyms: RNU6-1030P
Gene: Small nuclear RNA gene on chromosome 6 (31,756,951 to 31,757,053, reverse strand). Ensembl gene ENSG00000252743.
Homologues: Orthologues: chimpanzee U6 (98% identical), dog U6 (73% identical), dog U6 (68% identical), pig U6 (66% identical), guinea pig U6 (63% identical). Paralogues in human: RNU6-949P (84% identical), RNU6-1011P (83% identical), RNU6-24P (83% identical), RNU6-675P (83% identical), RNU6-698P (83% identical), RNU6-7 (83% identical), RNU6-8 (83% identical), RNU6-1 (83% identical), RNU6-11P (83% identical), RNU6-12P (83% identical), RNU6-1330P (83% identical), RNU6-13P (83% identical), and 1286 more.